FCGR2B (Fc gamma receptor IIb)
Description:
Receptor for the Fc region of complexed or aggregated immunoglobulins gamma. Low affinity receptor. Involved in a variety of effector and regulatory functions such as phagocytosis of immune complexes and modulation of antibody production by B-cells. Binding to this receptor results in down-modulation of previous state of cell activation triggered via antigen receptors on B-cells (BCR), T-cells (TCR) or via another Fc receptor. Isoform IIB1 fails to mediate endocytosis or phagocytosis. Isoform IIB2 does not trigger phagocytosis.
Synonyms: CD32; FCG2; IGFR2; CD32B; FcgammaRIIb; FcGRIIB; FCGR2
Tractability: Small molecule: a structure with a bound ligand is known. Antibody: a drug acting on it is in phase 2 or 3 trials; its Gene Ontology location is reachable by antibodies, with high confidence; UniProt places it where antibodies can reach, with medium confidence; UniProt predicts a signal peptide or a membrane-spanning region.
Gene: Protein-coding gene on chromosome 1 (161,662,803 to 161,679,490, forward strand). Ensembl gene ENSG00000072694.
Subcellular location: Cell membrane
Pathways (Reactome):
Immune System: Immunoregulatory interactions between a Lymphoid and a non-Lymphoid cell
Gene Ontology:
Molecular function: amyloid-beta binding; IgG binding; low-affinity IgG receptor activity; protein binding; protein-containing complex binding; IgG receptor activity
Biological process: Fc-gamma receptor signaling pathway; immune effector process; negative regulation of B cell receptor signaling pathway; phagocytosis; receptor-mediated endocytosis; regulation of dendritic spine maintenance; antibody-dependent cellular cytotoxicity; antigen processing and presentation of exogenous peptide antigen via MHC class II; cell surface receptor signaling pathway; cellular response to amyloid-beta; defense response; follicular B cell differentiation; follicular dendritic cell activation; immune complex clearance by monocytes and macrophages; immunoglobulin mediated immune response; inflammatory response; mature B cell differentiation involved in immune response; negative regulation of acute inflammatory response to antigenic stimulus; negative regulation of antibody-dependent cellular cytotoxicity; negative regulation of B cell activation; negative regulation of B cell proliferation; negative regulation of cytokine production; negative regulation of cytotoxic T cell degranulation; negative regulation of dendritic cell antigen processing and presentation; negative regulation of dendritic cell differentiation; and 19 more
Cellular component: plasma membrane; cell body; dendritic spine; external side of plasma membrane
Genetic constraint (gnomAD): Loss-of-function variants: 13 observed, 20.76 expected, observed/expected ratio (o/e) 0.63, 90% interval 0.41 to 1. The upper end of that interval is the gene's LOEUF score, 1, which puts it in group 4 of 6, group 1 being the genes least tolerant of losing a copy. Missense variants: 176 observed, 236.61 expected, observed/expected ratio (o/e) 0.74, 90% interval 0.66 to 0.84. Synonymous variants: 66 observed, 88.95 expected, observed/expected ratio (o/e) 0.74, 90% interval 0.61 to 0.91.
Cancer hallmarks: escaping programmed cell death (suppresses); suppression of growth (promotes)
Homologues: Orthologues: macaque FCGR2A (67% identical), guinea pig Fcgr2b (63% identical), mouse Fcgr2b (58% identical), rat Fcgr2b (53% identical), dog FCGR2B (50% identical), mouse Fcgr3 (40% identical), rat Fcgr2a (39% identical), rat Fcgr2al1 (38% identical), rat Fcgr2a (36% identical). Paralogues in human: FCGR2C (84% identical), FCGR2A (69% identical), FCGR1A (33% identical), FCGR3A (33% identical), FCGR3B (32% identical), FCRL5 (30% identical), FCER1A (27% identical), FCRL3 (27% identical), FCRLB (25% identical), FCRL4 (24% identical), FCRLA (19% identical), PECAM1 (19% identical), and 5 more.
Diseases named in the same sentence as FCGR2B in open-access papers:
FCGR2B is named in the same sentence as 203 diseases in open-access papers, as found by Europe PMC text mining. Sharing a sentence is not in itself a finding about the gene and the disease. The quoted sentences say what the papers report.
lupus (123 papers, 2010 to 2025). "At the same time, the overexpression of Tlr7 contributes to lupus phenotype in Yaa (Y-linked autoimmune acceleration) carrying mice, Tlr7 deficiency in Fcgr2b -deficient Yaa mice reduces plasma cell expansion and T cell activation." (PMID 38745067, 2024). "The researcher will use lupus laboratory animal models, specifically 6- to 8-month-old Fcgr2b-deficient lupus mice presenting high levels of autoantibodies and proteinuria." (PMID 38745067, 2024). "Administering ISD017 before the onset of anti-nuclear antibodies and lupus symptoms effectively reduced glomerulonephritis and autoantibody production in Fcgr2b-deficient mice." (PMID 38745067, 2024). "The STING inhibitor (ISD017) targeted STING signaling specifically and affected lupus development in the lupus-prone 129/B6.Fcgr2b-deficient mice." (PMID 38886451, 2024). "The Fcgr2b gene is located on chromosome 1, which contains several lupus susceptibility genes in humans and mice." (PMID 38745067, 2024). "Double-negative (DN) T cells are known to produce both IFN-γ and IL-17A in Fcgr2b-deficient lupus mice." (PMID 38886451, 2024). "Contrary to STING-induced dendritic cell expansion in Fcgr2b-deficient mice, these data suggested that cGAS signaling inhibited the accumulation of pDCs and activated DCs in the pristane-induced lupus model." (PMID 36591278, 2022). "Previous work suggests STING activation promotes DC maturation and pDC differentiation in Fcgr2b-deficient lupus mice." (PMID 36591278, 2022). "There are alleles of FCGR2B leading to loss of function or reduced expression that predisposes individuals to systemic lupus erythematosus (SLE)." (PMID 35819855, 2022). "Fcgr2b (Fc Gamma Receptor IIb) is a protein-coding gene associated with Systemic Lupus Erythematosus and Malaria." (PMID 36340779, 2022). "Alterations in the FCGR2B gene are associated with diseases such as systemic lupus erythematosus and rheumatoid arthritis, and its upregulation reduces the sensitivity of lymphoma to rituximab." (PMID 35111196, 2021). "Here, the renal ischemia reperfusion injury (I/R) was performed in Fc gamma receptor 2b deficient (Fcgr2b-/-) lupus mice and the in vitro experiments." (PMID 34248948, 2021). "Fc gamma receptor IIb (FcgRIIb) is the only inhibitory-FcgR in the FcgR family, and FcgRIIb-deficient (FcgRIIb−/−) mice develop a lupus-like condition with hyper-responsiveness against several stimulations." (PMID 33919603, 2021). "Research regarding conceptual STING targeted therapy has already been tested in mice, with positive preliminary results eliminating disease in Fcgr2b-deficient lupus mice." (PMID 34158841, 2021). "A single nucleotide polymorphism (SNP) in human FCGR2B (rs1050501) results in profound receptor dysfunction and is associated with increased susceptibility to lupus." (PMID 32541026, 2020). "Here, we demonstrated that disruption of STING signaling ameliorated lupus development in Fcgr2b-deficient mice." (PMID 33083760, 2020). "The adoptive transfer of STING-activated bone marrow-derived dendritic cells (BMDCs) into the double-deficiency (Fcgr2b−/−.Stinggt/gt) mice restored the lupus phenotypes." (PMID 33083760, 2020). "One cause of systemic lupus erythematosus (SLE) is the functional defect in Fc gamma receptor IIB (FcgRIIB)." (PMID 32582149, 2020). "The functional defect of Fc gamma receptor IIb (FcGRIIb), the only inhibitory receptor among FcGR family, is one of the genetic causes of systemic lupus erythematosus (SLE)." (PMID 31514375, 2019). "The defect on Fc gamma receptor IIb (FcγRIIb), the only inhibitory FcγR, has been identified as one of the genetic factors increasing susceptibility to lupus." (PMID 30034379, 2018). "Furthermore, STING-mediated signaling initiates lupus development in Fcgr2b-deficient lupus mice by expanding dendritic cells." (PMID 38745067, 2024).
lupus (continued). "In addition, many SNPs of FCGR2B are associated with an increased risk of systemic lupus erythematosus, an autoimmune disease known to be more prevalent in females than males." (PMID 38167211, 2024). "In Fc gamma receptor IIb- (Fcgr2b-) deficient mice that develop fatal lupus pathology, IL-17A/Act1 signaling has been shown to adversely affect the course of glomerulonephritis by promoting the recruitment of immune cells in particular neutrophils and NET deposition in inflamed kidneys." (PMID 35620115, 2022). "Additionally, STING mediates lupus in Fcgr2b-deficient mice through the expansion of dendritic cells." (PMID 36591278, 2022). "In the Fc gamma receptor 2b deficient (Fcgr2b-/-) mouse model of lupus, renal ischemia reperfusion injury promoted NETs in peripheral blood neutrophils and kidneys, which was followed by glomerular immunoglobulin (Ig) deposition and increased serum anti-dsDNA Ab." (PMID 35686129, 2022). "However, there has been controversy surrounding the predisposition to lupus in FcγRIIB-deficient mice, as some studies suggest that other genes in concordance with Fcgr2b are required to influence the development of lupus." (PMID 35819855, 2022). "In addition, the association between NETs and lupus exacerbation was demonstrated in renal I/R Fcgr2b-/- mice along with the inhibitors against NETs (Syk and PAD4 inhibitors)." (PMID 34248948, 2021). "To determine whether the Sting signaling is required for lupus development in the Fcgr2b−/− mice, we generated the double deficiency of Fcgr2b and Sting together with control littermates." (PMID 33083760, 2020). "Furthermore, we showed the vital role of STING in the Fcgr2b-deficient mice, one of the lupus mice models." (PMID 33083760, 2020). "Earlier studies have shown that 56R+/− mice on the C57BL/6 wt background produce autoreactive IgM and some IgG Abs, and that the introduction of the 56R allele into lupus-prone Fcgr2b−/− mice lead to increased IgG class switched autoAbs, particular of the 56R allele." (PMID 29928274, 2018). "The overexpression of FcγRIIb has also been shown to ameliorate disease in other lupus models, with FCGR2B being a strong susceptibility gene in SLE." (PMID 39007135, 2024). "Fcgr2b-deficient mice correspondingly developed the autoimmune lupus-like disease resembling human SLE." (PMID 37176021, 2023). "Furthermore, the lupus-associated polymorphism in human FCGR2B (rs1050501) that results in receptor dysfunction is associated with increased CCR7 expression on DCs following IgG IC stimulation, driving enhanced migration to the T cell zone of lymph nodes, propagating autoimmunity and inflammation." (PMID 35619690, 2022). "Moreover, immune hyper-responsiveness of innate immune cells (macrophages and neutrophils) is demonstrated in a lupus model from the loss of inhibitory Fc gamma receptor IIb (FcgRIIb), which induces prominent responses through the cross-link between activating-FcgRs and innate immune receptors." (PMID 35897790, 2022). "Fcgr2b is associated with systemic lupus erythematosus (SLE), a common autoimmune disease mostly associated with anti-dsDNA." (PMID 34248948, 2021). "Besides, the susceptibility to program cell death of Fcgr2b-/- neutrophils might be higher than WT cells that have been triggered the lupus activity." (PMID 34248948, 2021). "Because we recently demonstrated that T cell-independent B cell activation induces immunosuppressive sialylated IgG Abs in vivo, we wondered whether the introduction of the 56R allele into lupus-prone Fcgr2b−/− mice may lead to T cell-independent IgG autoAbs and provide a disease-protective effect." (PMID 29928274, 2018). "We previously demonstrated significant association of the polymorphism of the CD72 gene with susceptibility to human systemic lupus erythematosus (SLE) in individuals carrying a SLE-susceptible FCGR2B genotype (FCGR2B-232Thr/Thr)." (PMID 23268649, 2012).
lupus (continued). "The rs4657041 was the lead intronic cis-pQTL for FCGR2A and FCGR2B, which was shared with UC, systemic lupus erythematosus and various cell surface markers of different immune cell populations." (PMID 39512756, 2024). "LN cells from the dLNs of Fcgr2b-/- lupus-prone mice treated with PBS, dexamethasone and Dex-NPs were restimulated with apoptotic bodies and Treg populations were evaluated by flow cytometric analysis." (PMID 37176021, 2023). "Fcgr2b-/- lupus-prone mice were administered with PBS and the antigens mixed with dexamethasone or Dex-NPs and the dLNs were collected for the analysis of DCs and T cells by flow cytometry." (PMID 37176021, 2023). "Of interest, Fcgr2b-/- lupus-prone mice treated with dexamethasone or Dex-NPs exhibited less severe renal interstitial inflammation and lower glomeruli with mesangial expansion (third and fourth rows)." (PMID 37176021, 2023). "Of interest, Dex-NPs, but not dexamethasone, mediated the expansion of CD3+CD4+Foxp3+ Tregs and CD3+CD4+Foxp3+CD25+ activated Tregs in Fcgr2b-/- lupus-prone mice." (PMID 37176021, 2023). "Activation of STING participated in the development of lupus in Fcgr2b-deficient mice by promoting the maturation and differentiation of dendritic cells, whereas inhibition of STING signaling protected against lupus development." (PMID 37354378, 2023). "In mice with lupus phenotype mice (Fcgr2b-cKO mice), marginal zone B cells, B-1 cells, and plasma cells produce higher amounts of IgG3 than other subclasses." (PMID 37108090, 2023). "Compared to other mouse models of lupus diseases that have an intact expression of Fcgr2b (e.g., NZB/NZW), Fcgr2b-/- mice display strong autoimmunity with lupus phenotypes." (PMID 37176021, 2023). "Fc gamma receptor IIb (Fcgr2b) is associated with systemic lupus erythematosus (SLE), and Fcgr2b-/- mice develop age-related lupus features." (PMID 36211432, 2022). "After renal I/R treatment in Fcgr2b-/- lupus mice, NETs and apoptosis were found to be significantly induced in Fcgr2b-/- kidneys at 24 h post-IRI, and lupus nephritis was aggravated at 120 h post-IRI." (PMID 36211432, 2022). "The disruption of STING signaling relieves the lupus development in FCGR2B-deficient mice, and the transplantation of STING-activated bone marrow-derived dendritic cells into the mice with both FCGR2B and STING defects restores the lupus phenotype." (PMID 36172373, 2022). "In a recent study, a Syk inhibitor fostamatinib attenuated NETs in neutrophils and reduced lupus characteristics (serum creatinine, proteinuria, and anti-dsDNA) in Fcgr2b-/- lupus mice." (PMID 35686129, 2022). "Renal injury at 24 h post renal-I/R prominently induced neutrophil extracellular traps (NETs) and apoptosis in kidneys of Fcgr2b-/- lupus mice that exacerbated the lupus activity at 120 h post renal-I/R." (PMID 34248948, 2021). "In conclusion, renal I/R in Fcgr2b-/- mice induced lupus exacerbation at 120 h post-I/R injury partly because Syk-enhanced renal NETs led to apoptosis-induced anti-dsDNA, which was attenuated by a Syk inhibitor." (PMID 34248948, 2021). "Despite an incomplete data on the association between Syk and Fc gamma receptors, the attenuation of NETosis and apoptosis with the prevention on lupus exacerbation by Syk inhibitor in Fcgr2b-/- mice with renal-I/R is interesting." (PMID 34248948, 2021). "Here, we reported the in vitro and in vivo experiments to determine the effect of renal-I/R on lupus and evaluated the Syk inhibitor on Fcgr2b-/- lupus mice." (PMID 34248948, 2021). "Systemic lupus erythematosus (SLE) is a common autoimmune disease caused by a complex mixture of genetic and environmental factors and Fc gamma receptor IIb deficient (FcgRIIb-/-) mice have been used as a representative lupus model." (PMID 33573095, 2021). "In conclusion, the prominent NETs and the Syk activation were observed in Fcgr2b-/- mice after renal I/R injury that induced lupus exacerbation." (PMID 34248948, 2021).
lupus (continued). "The renal I/R was performed in 8-week-old Fcgr2b-/- mice, asymptomatic lupus prone condition, and age-matched WT mice demonstrated that there was a similar kidney injury between Fcgr2b-/- and WT mice at 24 h post-renal I/R." (PMID 34248948, 2021). "The IgG deposition at 120 h post I/R, which was a part of the wound healing process, was more profound in Fcgr2b-/- mice than WT, partly indicated an increased antibody production from ischemia induced inflammation in lupus mice." (PMID 34248948, 2021). "At 120 h post-renal I/R, Fcgr2b-/- mice demonstrated the lupus characteristics as indicated by Scr, anti dsDNA, proteinuria, and glomerular IC deposition." (PMID 34248948, 2021). "The prominent anti-dsDNA, which is a major lupus auto-antibody, in Fcgr2b-/- mice at 120 h post-renal I/R suggests an impact of the loss of immune tolerance in these lupus mice." (PMID 34248948, 2021). "Adoptive transfer of STING-activated bone marrow-derived dendritic cells into the FCGR2B and STING double-deficiency mice restored lupus phenotypes." (PMID 33083760, 2020). "To study how IgG Fc glycosylation is associated with the development of autoimmune pathology, we first used lupus-prone FcγRIIB knockout mice, a model of spontaneous lupus nephritis (Fcgr2b−/− females on the C57BL/6, haplotype b, background)." (PMID 29928274, 2018). "In line with that, serum IgG Abs from lupus-prone Fcgr2b−/− mice were less sialylated, compared to wild-type controls." (PMID 29928274, 2018). "We compared the frequencies of the functional SNPs of FCGR2A (FcγRIIa-H131R, rs1801274), FCGR2B (FcγRIIb-I232T, rs1050501), FCGR3A (FcγRIIIa-V158F, rs396991) and FCGR3B variants (FcγRIIIb NA1 and NA2) between lupus and healthy controls in an indigenous African Caribbean population." (PMID 40728959, 2025). "We intraperitoneally injected symptomatic Fcgr2b−/− mice (5–6 months old) with ISD017 or cyclophosphamide to determine whether ISD017 can be used as a treatment for overt lupus phenotypes compared to the standard treatment, cyclophosphamide." (PMID 38745067, 2024). "Thus, the Fcgr2b-deficient lupus mouse is a relevant model for studying human SLE pathogenesis." (PMID 38745067, 2024). "The absence of stimulator of interferon genes (STING) in 129.B6.Fcgr2b-deficient mice rescue lupus phenotypes." (PMID 38745067, 2024). "Furthermore, Dex-NPs produced great therapeutic effects in Fcgr2b-/- lupus-prone mice by mediating the selective targeting to DCs probably in a particle size-dependent manner and, as a consequence, inducing Treg expansion and antigen-specific immune tolerance." (PMID 37176021, 2023). "In addition, dexamethasone and Dex-NP treatment significantly reduced proteinuria (urine protein creatinine index; UPCI) in Fcgr2b-/- lupus-prone mice." (PMID 37176021, 2023). "The substantial number of Tregs in Dex-NPs treated lupus mice may primarily depend on IL-10 production by DCs since Dex-NPs, but not dexamethasone, induced high IL-10 production in both WT and Fcgr2b-/- DCs." (PMID 37176021, 2023). "Our previous study showed STING-mediated lupus in a spontaneous mouse model, Fcgr2b-deficient mice, through both IFN-I and non-IFN-I signaling pathways." (PMID 36591278, 2022). "Indomethacin (25 mg/day) was orally administered for 7 days in 24-wk-old Fc gamma receptor IIb deficient (FcgRIIb-/-) mice, an asymptomatic lupus model (increased anti-dsDNA without lupus nephritis), and age-matched wild-type (WT) mice." (PMID 33573095, 2021). "In contrast, all the organ injury and serum cytokines in Fcgr2b-/- mice highly increased at 120 h post I/R with elevated anti-dsDNA, suggesting an exacerbation of lupus disease activity." (PMID 34248948, 2021). "In this study, plasma cells and activated B cells in spleen of Fcgr2b-/- mice were higher than WT at 120 h post-renal I/R, supporting that a prominent activity of these immune cells in lupus that might be responsible for the rapid induction of anti-dsDNA." (PMID 34248948, 2021).